RUFY3 (RUN and FYVE domain containing 3)
Description:
ARL8 effector that promotes the coupling of endolysosomes to dynein-dynactin for retrograde transport along microtubules. Acts by binding both GTP-bound ARL8 and dynein-dynactin. In nonneuronal cells, promotes concentration of endolysosomes in the juxtanuclear area. In hippocampal neurons, drives retrograde transport of endolysosomes from the axon to the soma. Plays a role in the generation of neuronal polarity formation and axon growth (By similarity). Implicated in the formation of a single axon by developing neurons (By similarity). May inhibit the formation of additional axons by inhibition of PI3K in minor neuronal processes (By similarity). Plays a role in the formation of F-actin-enriched protrusive structures at the cell periphery. Plays a role in cytoskeletal organization by regulating the subcellular localization of FSCN1 and DBN1 at axonal growth cones (By similarity).
Synonyms: RIPx; KIAA0871; Singar1; ZFYVE30
Tractability: PROTAC: ubiquitination databases record sites on it; its protein half-life has been measured.
Gene: Protein-coding gene on chromosome 4 (70,704,204 to 70,808,619, forward strand). Ensembl gene ENSG00000018189.
Subcellular location: Cytoplasm; Endomembrane system; Cell projection, invadopodium; Perikaryon; Cell projection; Cell projection, growth cone; Cell projection, filopodium; Cell projection, lamellipodium; Lysosome
Subcellular location (Human Protein Atlas): Cytosol
Gene Ontology:
Molecular function: dynactin binding; protein binding
Biological process: positive regulation of cell migration; positive regulation of retrograde axon cargo transport; actin filament organization; negative regulation of axonogenesis; positive regulation of axon extension; positive regulation of intracellular protein transport; regulation of axonogenesis; regulation of establishment of cell polarity
Cellular component: cytoplasm; cytosol; endolysosome; endomembrane system; lysosome; axon; dendrite; filopodium; growth cone; lamellipodium; neuronal cell body; perikaryon
Genetic constraint (gnomAD): Loss-of-function variants: 23 observed, 47.27 expected, observed/expected ratio (o/e) 0.49, 90% interval 0.35 to 0.69. The upper end of that interval is the gene's LOEUF score, 0.69, which puts it in group 2 of 6, group 1 being the genes least tolerant of losing a copy. Missense variants: 320 observed, 503.79 expected, observed/expected ratio (o/e) 0.64, 90% interval 0.58 to 0.7. Synonymous variants: 164 observed, 178.06 expected, observed/expected ratio (o/e) 0.92, 90% interval 0.81 to 1.05.
Homologues: Orthologues: chimpanzee RUFY3 (99% identical), rabbit RUFY3 (95% identical), pig RUFY3 (94% identical), dog RUFY3 (88% identical), mouse Rufy3 (85% identical), rat Rufy3 (85% identical), guinea pig RUFY3 (77% identical), tropical clawed frog rufy3 (71% identical), zebrafish rufy3 (60% identical), Drosophila melanogaster CG31064 (42% identical), Drosophila melanogaster CG6051 (13% identical), Caenorhabditis elegans lst-2 (11% identical). Paralogues in human: RUFY2 (51% identical), RUFY1 (49% identical), ZFYVE26 (18% identical), RUNDC3B (18% identical), RUNDC3A (18% identical), SNX29 (18% identical), PLEKHM2 (17% identical), ZFYVE28 (15% identical), ZFYVE1 (15% identical), ZFYVE19 (12% identical), ZFYVE16 (9% identical), PLEKHF1 (7% identical), and 1 more.
Diseases named in the same sentence as RUFY3 in open-access papers:
RUFY3 is named in the same sentence as 25 diseases in open-access papers, as found by Europe PMC text mining. Sharing a sentence is not in itself a finding about the gene and the disease. The quoted sentences say what the papers report.
gastric cancer (10 papers, 2015 to 2022). A primary or metastatic malignant neoplasm involving the stomach. "A gastric cancer study found that Rufy3 promoted gastric cancer cell invasion and migration by causing the formation of Factin-enriched protrusive structures in the cell periphery." (PMID 35461284, 2022). "The results also showed that high levels of PAK1 and RUFY3 appear to be associated with the progression and metastasis of human gastric cancer, which indicated that the expression level of RUFY3 by immunohistochemistry are correlated with PAK1, consistent with western blot results." (PMID 25766321, 2015). "For instance, RUFY3 is involved in F-actin-enriched protrusions from the cell surface and it has been shown to be involved in gastric cancer cell migration and invasion." (PMID 34149812, 2021). "Recently one research showed that in gastric cancer, RUFY3 can interact with activated P21 kinase-1 (PAK1) and promote gastric cancer metastasis." (PMID 31772661, 2019). "P21-activated kinase-1 (PAK1) interacts with RUFY3, resulting in RUFY3-induced gastric cancer cell migration." (PMID 28623323, 2017). "As expected, knockdown of RUFY3 inhibited gastric cancer cell migration and invasion compared with control siRNA cells." (PMID 25766321, 2015). "Strikingly, we found significant upregulation of RUFY3 in gastric cancer samples with invasive carcinoma at pathologic TNM III and TNM IV stages, compared with their non-tumor counterparts." (PMID 25766321, 2015). "Here, our data show that overexpression of RUFY3 leads to the formation of F-actin-enriched protrusive structures at the cell periphery and induces gastric cancer cell migration." (PMID 25766321, 2015). "In gastric cancer samples, we showed a positive relationship between PAK1 and RUFY3, and that increased expression of RUFY3 is positively correlated with clinical gastric cancer samples." (PMID 25766321, 2015). "The purpose of this study was to elucidate the molecular mechanisms by which RUFY3 involves in gastric cancer cell migration and invasion." (PMID 25766321, 2015). "For example, RUFY3 is located in the invasion foot rich in F-actin, which induces the formation of protrusion structure and plays an important role in the migration and invasion of gastric cancer cell." (PMID 34510031, 2021). "Importantly, we found that the overexpression of RUFY3 promotes gastric cancer cell migration and invasion." (PMID 25766321, 2015). "Therefore, our results indicated that PAK1 regulated RUFY3-mediated gastric cancer cell migration and invasion." (PMID 25766321, 2015). "Furthermore, P21-activated kinase-1 (PAK1) interacts with RUFY3, and promotes RUFY3 expression and RUFY3-induced gastric cancer cell migration; inhibition of PAK1 attenuates RUFY3-induced SGC-7901 cell migration and invasion." (PMID 25766321, 2015). "Furthermore, we showed that PAK1 can affect RUFY3-mediated gastric cancer cell migration and invasion by regulating its expression." (PMID 25766321, 2015). "To test the role of RUFY3 in HOXD9-mediated tumor progression, we have established tail-vein metastasis model and orthotropic implantation model using human gastric cancer AGS cells in nude mice, which resulted in lung and liver metastases." (PMID 31547840, 2019). "We also found that the protein expressions of RUFY3 and PAK1 positively correlate with human clinical gastric cancer samples." (PMID 25766321, 2015). "The 10 representative samples of gastric cancer showed a positive correlation expression between PAK1 and RUFY3." (PMID 25766321, 2015). "We also analyzed the levels of RUFY3 and PAK1 by immunohistochemistry in 40 gastric cancers specimen including metastatic tumors." (PMID 25766321, 2015). "RUFY3 overexpression and its interaction with P21-activated kinase-1 (PAK1) leads to the formation of F-actin-enriched protrusive structures, increased epithelial-mesenchymal transition and gastric cancer cell migration." (PMID 32850870, 2020).
gastric cancer (continued). "Interestingly, RUN and FYVE domain containing 3 (RUFY3), which can be up-regulated by PAK1, localizes with F-actin and formats F-actin-enriched protrusive structures to promote gastric cancer cells migration and invasion." (PMID 32863957, 2020). "In addition, we measured the protein levels of RUFY3 and PAK1 in 40 pairs of gastric cancer tissue samples with invasive carcinoma at pathologic TNM III and TNM IV stages through western blot." (PMID 25766321, 2015). "Moreover, an obvious positive correlation was observed between the protein expression of RUFY3 and PAK1 in 40 pairs of gastric cancer samples." (PMID 25766321, 2015). "To examine the role of RUFY3 and its relationship with PAK1 in gastric cancer, we first investigated the protein levels of RUFY3 and PAK1 in gastric cancer cell lines (BGC-823, MKN45, AGS, MGC-803, SGC-7901 and MKN1) relative to the normal gastric epithelial cell line (GES-1) by western blot." (PMID 25766321, 2015). "Therefore, based on these results, we draw a conclusion that PAK1 regulates RUFY3-mediated gastric cancer cell migration and invasion, suggesting that blocking PAK1-RUFY3 pathway might be a potential therapeutic strategy for metastasis of gastric cancer." (PMID 25766321, 2015).
colorectal cancer (4 papers, 2017 to 2022). A primary or metastatic malignant neoplasm that affects the colon or rectum. "Another study about colorectal cancer conducted by the same team showed that RUFY3 can interact with FOCK1 and play a role in invasion and metastasis." (PMID 31772661, 2019). "Xie's team demonstrated that RUFY3 had a high expression level in colorectal cancer, and could promote cell proliferation, migration, and invasion." (PMID 31772661, 2019). "Another research showed that RUFY3 can interact with FOXK1 and promotes invasion and metastasis in colorectal cancer." (PMID 31772661, 2019).
amyotrophic lateral sclerosis (2 papers, 2017 to 2020). Amyotrophic lateral sclerosis (ALS) is a neurodegenerative disease characterized by progressive muscular paralysis reflecting degeneration of motor neurons in the primary motor cortex, corticospinal tracts, brainstem and spinal cord. "A recent study showed a significant up-regulation of MEF2C and MEF2D mRNA levels in both sporadic and SOD1+ amyotrophic lateral sclerosis (ALS) patients detected by gene expression analysis, and a down-regulation of their targets, BDNF, KLF6, and RUFY3." (PMID 29340119, 2017). "RUFY3 seems therefore to have different axogenic functions in brain and not surprisingly, roles for RUFY3 in amyotrophic lateral sclerosis, major depressive disorder and AD have been reported." (PMID 32850870, 2020).
hepatocellular carcinoma (2 papers, 2021 to 2024). A malignant tumor that arises from hepatocytes. "However, the exact role of RUFY3 in hepatocellular carcinoma (HCC) progression remains elusive." (PMID 34510031, 2021). "RUFY3 encodes a protein that contains the structural domains of RPIP8, UNC-14, and NESCA and has been reported to promote cell migration and invasion in gastric and hepatocellular carcinomas, but this phenomenon has not been reported in lung cancer studies." (PMID 38915053, 2024).
lung adenocarcinoma (2 papers, 2019 to 2022). A carcinoma that arises from the lung and is characterized by the presence of malignant glandular epithelial cells. "RUFY3 expression was assessed in association with clinicopathological characteristics and clinical prognosis of lung adenocarcinoma patients." (PMID 31772661, 2019). "In summary, these result showed that RUFY3 can affect the migration and invasion of lung adenocarcinoma cells." (PMID 31772661, 2019). "Materials and Methods: We used immunohistochemistry to detect RUFY3 protein expression in human lung adenocarcinoma and adjacent normal lung tissue from 125 patients who underwent surgical resection of the lung cancer." (PMID 31772661, 2019). "All patients were divided into two groups according to mean expression level to investigate the importance of RUFY3 overexpression in predicting clinical outcomes of lung adenocarcinoma patients." (PMID 31772661, 2019). "In the present study, we first used immunochemistry assay to identify expression of RUFY3 in human lung adenocarcinoma and adjacent normal tissues." (PMID 31772661, 2019). "The expression of RUFY3 in three different lung adenocarcinoma cell lines and one normal lung epithelial cell (BEAS-2B) was detected by western blot." (PMID 31772661, 2019). "Here, we showed that inhibiting the expression of RUFY3 in lung adenocarcinoma cells has an effect on the expression of key molecules in the EMT pathway." (PMID 31772661, 2019). "The expression level of RUFY3 in lung adenocarcinoma was significantly higher than that in normal tissues." (PMID 31772661, 2019). "In summary, our study was first to identify RUFY3 expression pattern and investigated its relationship with clinicopathological characteristics of lung adenocarcinoma patients." (PMID 31772661, 2019). "Multiple Cox regression analysis showed that high expression level of RUFY3 (P=0.044) and tumor size (P=0.014) were independent prognostic factors of lung adenocarcinoma." (PMID 31772661, 2019). "In the present study, we aimed to study the expression of RUFY3 and assess its clinical significance in lung adenocarcinoma." (PMID 31772661, 2019). "This highlights the potential of RUFY3 as a novel prognostic biomarker for lung adenocarcinoma." (PMID 31772661, 2019). "According to Kaplan Meier survival analysis, there was a negative association between RUFY3 expression and OS of lung adenocarcinoma patients." (PMID 31772661, 2019). "In addition, we used Western blot to detect the expression of RUFY3 in different lung adenocarcinoma cell lines." (PMID 31772661, 2019). "However, after adjusting tumor size, lymph node metastasis, and TNM staging, multiple Cox regression revealed that RUFY3 expression could be considered an independent factor for predicting survival in lung adenocarcinoma patients." (PMID 31772661, 2019). "Our results suggest that RUFY3 may act as a novel therapeutic target in lung adenocarcinoma." (PMID 31772661, 2019). "RUFY3 depletion in other cell types, including ARPE-19 (retinal pigment epithelial cells), U2OS (osteosarcoma cells), and A549 (lung adenocarcinoma cells), showed a similar distribution of lysosomes towards the cell periphery." (PMID 35314681, 2022). "Furthermore, we analyzed the expression of RUFY3 and EMT markers (E-cadherin, N-cadherin, Vimentin and Slug) in 2 lung adenocarcinoma cell lines after RUFY3 silencing by Western blot." (PMID 31772661, 2019).
lung carcinoma (2 papers, 2019 to 2024). "By exploring the underlying mechanism, we found that circSORBS1 regulates RUFY3 expression directly and indirectly, activates the YWHAE/BAD/BCL2 apoptosis signalling pathway, and ultimately inhibits the development of lung cancer." (PMID 38915053, 2024). "To further explore the regulatory mechanism of circSORBS1 in lung cancer development, we investigated the signalling pathways downstream of RUFY3." (PMID 38915053, 2024). "The level of RUFY3 expression in lung cancer tissues was significantly higher than in adjacent normal tissue (IS, 6.12 ± 3.58 versus 4.71 ± 3.06, respectively, P = 0.007)." (PMID 31772661, 2019). "In the 125 lung cancer specimens and adjacent lung tissue, using the immunohistochemical assay we can see that RUFY3 mainly appeared in the cytoplasm in either cancer or normal tissues." (PMID 31772661, 2019). "Therefore, we attempted to elucidate the mechanism by which circSORBS1 inhibits lung cancer development by regulating the RUFY3/YHWAE/BAD/BCL2 pathway through rescue experiments." (PMID 38915053, 2024). "In lung cancer, we were the first to find that RUFY3 interacts with YWHAE." (PMID 38915053, 2024). "Concerning the expression level of RUFY3 and clinical characteristics of lung cancer, we discovered that higher expression of RUFY3 may also be associated with lymph node metastasis and TNM staging." (PMID 31772661, 2019). "This dual regulatory mechanism leads to an increase in RUFY3 protein levels, which ultimately activates the YWHAE/BAD/BCL2 apoptotic signalling pathway and suppresses lung cancer progression." (PMID 38915053, 2024). "In summary, we elucidated that circSORBS1 activates the RUFY3/YWHAE/BAD/BCL2 signalling pathway through both a sponging mechanism and direct mRNA binding, ultimately inhibiting the development of lung cancer." (PMID 38915053, 2024). "Currently, there are few studies on RUFY3, and the function of RUFY3 in lung cancer and its mechanism have not been fully elucidated." (PMID 38915053, 2024).
major depression (2 papers, 2020 to 2023). "Relevant differentially methylated regions in the blood of patients with major depression significantly overlap with differentially methylated regions in the Brodmann area of the brain and yield three CpG pooling sites in the brain: GABBR2, RUFY3 and an intergenic region on chromosome 2." (PMID 37140907, 2023).
metastatic cancer (2 papers, 2017 to 2019). A carcinoma which has spread from the original site of growth to another anatomic site. "Furthermore, we examined the expression of HOXD9 and RUFY3 in serial sections of lymph node metastatic cancer tissues from two patients." (PMID 31547840, 2019). "To validate our findings in vivo, we detected RUFY3 and FOXK1 in serial sections of lymph node metastatic cancer tissues from two patients." (PMID 28623323, 2017).
metastatic tumor (2 papers, 2015 to 2020). "Given the key role of RUFY3 in cell migration, membrane transport, and cellular signaling, through its interaction with rap2, it is not surprising that RUFY3 dysregulation has been implicated in several cancer processes and metastatic tumor spread." (PMID 32850870, 2020).
breast carcinoma (1 paper, 2023). "In order to characterize the functional association among HPIP, RUFY3, and Rab5, we first examined their expression in a panel of breast cancer cells." (PMID 37797694, 2023). "Together the results from these studies imply that Rab5-mediated FAK activation and FA dynamics are attributed to the Rab5 GEFs function of HPIP and RUFY3 in breast cancer cells." (PMID 37797694, 2023).
hemorrhagic stroke (1 paper, 2022). A stroke caused by a bleed on the brain. "Therefore, the Rufy3/Rap1 complex may be a therapeutic target for hemorrhagic stroke." (PMID 35461284, 2022).
liver cancer (1 paper, 2018). An epithelial or non-epithelial malignant neoplasm that arises from the liver. "Although Pak1 was up-regulated in tumor compared to normal samples, it is also observed in TCGA liver cancer datasets, and thus not in a Rufy3-specific manner." (PMID 30060537, 2018).
lymph node metastasis (1 paper, 2019). "The single Cox regression shows that RUFY3 expression, tumor size, lymph node metastasis, and TNM stage were all risk factors for patient prognosis." (PMID 31772661, 2019). "We have showed that higher expression of RUFY3 was associated with lymph node metastasis and TNM staging." (PMID 31772661, 2019). "High cytoplasmic RUFY3 levels were associated with lymph node metastasis, TNM staging, and survival status." (PMID 31772661, 2019). "In patients with lymph node metastasis positive expression rate of RUFY3 (41/63, 65.1 %) was much higher than in those without lymph node metastasis (27/62, 43.5%)." (PMID 31772661, 2019).
Salmonella Infections (1 paper, 2023). Infections with bacteria of the genus SALMONELLA. "Experiments performed in EBSS conditions to enhance ELs perinuclear concentration, revealed that Salmonella infection fully prevents LAMP1 clustering presumably by recruiting RUFY3 to the SCV." (PMID 37463962, 2023). "To test functionally the impact of RUFY3 on EL function, we performed Salmonella infection, since ARL8b/PLEKHM2/HOPS- and Rab7/PLEKHM1-dependent EL mobilizations are particularly important for the maturation of Salmonella-containing vacuoles (SCV) and bacterial replication in macrophages." (PMID 37463962, 2023).
subarachnoid hemorrhage (1 paper, 2022). A serious neurological disorder characterized by intracranial hemorrhage into the subarachnoid space. "However, in experimental subarachnoid hemorrhage (SAH), the role of Rufy3 has not been investigated." (PMID 35461284, 2022).